OR8H2 (olfactory receptor family 8 subfamily H member 2)
Description:
Odorant receptor.
Synonyms: OR11-171
Tractability: Antibody: UniProt places it where antibodies can reach, with medium confidence; UniProt predicts a signal peptide or a membrane-spanning region; its Gene Ontology location is reachable by antibodies, with medium confidence.
Gene: Protein-coding gene on chromosome 11 (56,103,687 to 56,107,658, forward strand). Ensembl gene ENSG00000181767.
Subcellular location: Cell membrane
Pathways (Reactome):
Sensory Perception: Expression and translocation of olfactory receptors
Gene Ontology:
Molecular function: olfactory receptor activity; G protein-coupled receptor activity
Biological process: G protein-coupled receptor signaling pathway; sensory perception of smell; detection of chemical stimulus involved in sensory perception of smell
Cellular component: plasma membrane; membrane
Genetic constraint (gnomAD): Missense variants: 363 observed, 361.8 expected, observed/expected ratio (o/e) 1, 90% interval 0.92 to 1.09. Synonymous variants: 154 observed, 138.33 expected, observed/expected ratio (o/e) 1.11, 90% interval 0.98 to 1.27.
Homologues: Orthologues: chimpanzee OR8H2 (97% identical), macaque OR8H3 (91% identical), rat Or8h10 (72% identical), rat Or8h6 (72% identical), mouse Or8h6 (71% identical), rat Or8h10c (71% identical), mouse Or8h10 (71% identical), mouse Or8h9 (70% identical), rat Or8h11 (70% identical), mouse Or8h8 (70% identical), mouse Or8h7 (69% identical), rat Or8h9 (69% identical), and 2 more. Paralogues in human: OR8H3 (92% identical), OR8H1 (87% identical), OR8I2 (56% identical), OR5F1 (52% identical), OR5B12 (51% identical), OR8D4 (51% identical), OR5B21 (50% identical), OR5M8 (50% identical), OR5A1 (50% identical), OR8A1 (49% identical), OR5B17 (49% identical), OR8U3 (49% identical), and 84 more.